SPP1 (secreted phosphoprotein 1)
Diseases named in the same sentence as SPP1 in open-access papers (continued):
Sharing a sentence is not in itself a finding about the gene and the disease.
COVID-19 (continued). "In CSF, innate immune genes SPP1, CXCL10, and TNFRSF1B are differentially expressed in COVID-19 vs. non-COVID-19 patients." (PMID 34108016, 2021). "Thus, COVID-19 pneumonitis appears driven by similar pathogenic myeloid cell pathways as those in RA, and their mediators such as SPP1 may be an upstream activator of the aberrant innate response in severe COVID-19 and predictive of disease trajectory including post–COVID-19 monitoring." (PMID 34143756, 2021). "Patients with acute COVID-19 had significantly higher plasma levels of proinflammatory SPP1 and S100A12 than healthy donors and patients at the post–COVID-19 stage." (PMID 34143756, 2021). "However, it increased expression levels of alarmins S100A12 and S100A9, and it decreased the expression of MHCII and ENTPD1 of CD14+ monocytes, suggesting that persistent levels of SPP1 may contribute to long–COVID-19 pathologies by skewing monocytes toward a proinflammatory phenotype." (PMID 34143756, 2021). "We found that — in contrast, for example, to IL-6 — plasma SPP1 and S100A12 remained significantly higher than normal for at least 10 weeks after infection clearance in the post–COVID-19 convalescent phase." (PMID 34143756, 2021). "COVID-19 BALF FCN1+ and FCN1+SPP1+ macrophage clusters are transcriptionally similar to CD48hiS100A12+ and CD48+SPP1+ clusters that drive RA synovitis." (PMID 34143756, 2021). "Macrophage subset classification markers, including FCN1, SPP1, and FABP4, were differentially expressed by circulating and BALF monocyte-macrophages from patients with mild or severe COVID-19." (PMID 33101705, 2020). "Moreover, in severe COVID-19, alternative M2 macrophages have been reported to express TREM2, TGFB1, and SPP1, which are profibrotic genes and immunoregulatory genes including A2M and GPR3." (PMID 35002519, 2022). "The hierarchical analysis and comparison of cluster markers also indicate a shared transcriptional profile of COVID-19 FCN1+SPP1+ and synovitis CD48+SPP1+ clusters consisting of 86 common marker genes including SPP1, which have broad proinflammatory and fibrotic functions." (PMID 34143756, 2021). "The alveolar tissue of COVID-19 patients abundantly presents two distinct macrophage clusters expressing ficolin-1 (FCN1), which can be differentiated by their relative expression of secreted phosphoprotein 1/osteopontin (SPP1)." (PMID 34943795, 2021). "We identified several AD marker genes (e.g., NKTR, GSTM3, TGFB1, TNFRSF1B, SPP1, and CXCL10) which may provide insights into the shared pathobiology of cognitive dysfunction in COVID-19 and AD." (PMID 34108016, 2021). "SPP1 at post–COVID-19 convalescent plasma concentration (50 ng/mL) did not affect neutrophil activation." (PMID 34143756, 2021). "Moreover, SPP1 and S100A12 each strongly correlated with the neutrophil/lymphocyte ratio, which itself is a prognostic biomarker for COVID-19 severity." (PMID 34143756, 2021). "COVID-19 patients with severe respiratory distress were characterized by an aberrant raised SPP1 and S100A12 cytokine signature that could predict the urgency for ICU transfer and persisted into the post–COVID-19 phase after hospital discharge." (PMID 34143756, 2021). "Investigation into SPP1 mechanisms of action revealed that it drives proinflammatory activation of CD14+ monocytes and development of PD-L1+ neutrophils, both hallmarks of severe COVID-19." (PMID 34143756, 2021). "Finally, since MAFB-dependent factors like IL-10, SPP1, CCL2, and CXCL13 are biomarkers for COVID-19 severity, we next assessed whether additional MAFB-dependent soluble factors might also predict COVID-19 severity or outcome." (PMID 37917179, 2023). "However, the reduced PROS1, which is the preferred activating ligand for MerTK, and the fewer homeostatic resident AMs in severe COVID-19 might enable unrestricted proinflammatory cytokine production by locally differentiated MerTK-expressing FCN+ and FCN+SPP1+ macrophages." (PMID 34143756, 2021).
COVID-19 (continued). "Stratification of patients by symptoms showed that SPP1 and S100A12 levels remained increased and GAS6 decreased in convalescent COVID-19 patients, irrespective of symptom category." (PMID 34143756, 2021). "However, although reduced, the levels of SPP1 and S100A12 remained significantly higher than in healthy control donors, irrespective of whether the prior disease trajectory of COVID-19 was mild/moderate or severe." (PMID 34143756, 2021).
Insulin resistance (59 papers, 2009 to 2026). Increased resistance towards insulin, that is, diminished effectiveness of insulin in reducing blood glucose levels. "SPP1 also known as Osteopontin is an inflammatory cytokine which is highly upregulated in obesity and has been shown to be a key player for local adipose tissue macrophage proliferation which underlies insulin resistance and type 2 diabetes." (PMID 34041258, 2021). "A link to cardiovascular disease is apparent: SPP1 is involved in atherosclerotic plaque formation, ischaemic heart disease progression, and insulin resistance." (PMID 39919333, 2025). "Previous studies have shown that the expression of SPP1 was positively correlated with liver steatosis, inflammation, fibrosis and insulin resistance in obese individuals or mice." (PMID 36911682, 2023). "OSM treatment regulates the expression of many proinflammatory adipokines causing insulin resistance (Timp1, PAI-1, Igfbp3, and Spp1) in adipose tissue." (PMID 31576964, 2020). "SPP1 also has roles in adipose tissue and contributes to adipose tissue inflammation and insulin resistance." (PMID 33076817, 2020). "In addition, Elks CM and colleagues also observed that treatment with oncostatin M induced gene expression of Timp1, Igfbp3, and Spp1 while alleviating insulin resistance." (PMID 38397957, 2024). "Moreover, similar results were proved in the expression levels of SPP1 and ALP, Expression was higher in T2D cells in comparison to the control (SPP1, p = 0.0001; ALP, p < 0.0001) and to cells from patients with insulin resistance (SPP1, p < 0.0001; ALP, p = 0.0263)." (PMID 32615920, 2020). "In addition, MMP9, TIMP1, SPP1 and POSTN were shown to play a role in regulating fat metabolism and insulin resistance." (PMID 35966072, 2022).
multiple sclerosis (56 papers, 2006 to 2025). A progressive autoimmune disorder affecting the central nervous system resulting in demyelination. "Studies have identified that elevated levels of SPP1 are associated with increased neuroinflammation and neurodegeneration; thus, SPP1 is upregulated in several neuro-disorders, including multiple sclerosis, AD, and age-related macular degeneration." (PMID 40004604, 2025). "The SPP1 gene encodes osteopontin (OPN), a protein that has aroused interest as a therapeutic target in several immune and inflammatory diseases, including multiple sclerosis as a neurological condition." (PMID 38001994, 2023). "In multiple sclerosis, SPP1 mediates pro-inflammatory pathways contributing to the relapse remission phenotype via e.g. NF-κB." (PMID 31887157, 2019). "SPP1 levels in CSF were also elevated in Alzheimer’s disease and mild cognitive impairment, and multiple sclerosis patients." (PMID 27186164, 2016). "Spp1/OPN were also detected in central nervous system, where they may play a role in neurodegenerative diseases, such as Alzheimer's disease, Parkinson's disease, and multiple sclerosis." (PMID 31057484, 2019).
cervical carcinoma (52 papers, 2006 to 2026). A carcinoma arising from either the exocervical squamous epithelium or the endocervical glandular epithelium. "Cox regression analysis identified 35 genes independently associated with the prognosis of cervical cancer, of which SPP1, LYZ, and MCM5 were significantly regulated in both RA and cervical cancer." (PMID 41384115, 2025). "In correlation, a recent TAN profiling study also reported that the VEGFA + SPP1+ subset was associated with worse clinical outcomes in 225 samples from 145 patients of 17 solid tumors including cervical cancer." (PMID 39971940, 2025). "Further exploration revealed that higher SPP1 expression was associated with reduced overall survival (OS) in cervical cancer patients." (PMID 35058964, 2021). "In univariate Cox analysis of SPP1, T stage (P = 0.025), N stage (P = 0.002), M stage (P = 0.023), and SPP1 expression (P = 0.032) were associated with overall survival (OS) in cervical cancer patients." (PMID 35058964, 2021). "In the study by Cho, SPP1 had a 50.6% sensitivity and 95.0% specificity as a diagnostic biomarker for cervical cancer." (PMID 32300605, 2020). "SPP1 encodes a protein which is a cytokine that upregulates expression of interferon-gamma and interleukin-12, and it is an unfavorable prognostic marker in liver, pancreatic, and cervical cancer." (PMID 34830910, 2021). "Of particular note is the over expression of the gene SPP1, which could potentially serve as serum diagnostic marker for cervical cancer." (PMID 24403257, 2013). "However, the expression patterns, prognostic significance, and underlying molecular mechanisms of CXCL9 and SPP1 in cervical cancer remain unclear." (PMID 40936719, 2025). "Functional validation indicated that upregulated FASN and SPP1 contribute to malignant behaviors in cervical cancer cells." (PMID 42198359, 2026). "Intersection analysis revealed 18 genes that were significantly differentially expressed, including the five selected biomarkers (MMP1, RNF2, TFRC, SPP1, and CXCL8), which are significantly associated with cervical cancer progression." (PMID 40809844, 2025). "The upregulated ligand receptor pairs in the cervical cancer group were SPP1 − CD44, FN1 − SDC4, FN1 − SDC1, FN1 − CD44, CD99 − CD99, and the downregulated ligand receptor pairs were PPIA – BSG, LGALS9 − P4HB, LGALS9 − CD44." (PMID 41384115, 2025). "The expression ratio of CXCL9 to SPP1 was analyzed in cervical cancer patients using data from the Gene Expression Omnibus (GEO) database, which revealed significant differences." (PMID 40936719, 2025). "Compared with cervical cancer patients, SPP1 (p = 0.005), LYZ (p = 0.005) and MCM5 (p = 0.006) were also highly expressed in RA combined with cervical cancer, and the difference was statistically significant." (PMID 41384115, 2025). "Even though our study showed that SPP1, LYZ, and MCM5 have good clinical value and diagnostic performance in patients with cervical cancer and RA, there are still certain limitations." (PMID 41384115, 2025). "In this study, we identified five ubiquitination-related biomarkers (MMP1, RNF2, TFRC, SPP1, and CXCL8) that are significantly associated with cervical cancer." (PMID 40809844, 2025). "Poleboyina PK identified SPP1 as highly upregulated in cervical cancer and noted that entrectinib, an SPP1 inhibitor, effectively slows cancer progression." (PMID 41391064, 2025). "Future studies should focus on collecting patients with RA and cervical cancer for high throughput sequencing to further reveal the role of SPP1, LYZ, and MCM5 in the disease." (PMID 41384115, 2025). "The findings showed that cervical cancer tissues had increased expression levels of SPP1 (p = 0.047), LYZ (p = 0.034), and MCM5 (p = 0.002) in comparison to the healthy control group; this difference was statistically significant." (PMID 41384115, 2025).
cervical carcinoma (continued). "The results showed that SPP1, LYZ, and MCM5 not only had high diagnostic potential in patients with RA and cervical cancer but also showed specific binding sites with HPV 16 E6/E7 proteins through molecular docking simulation." (PMID 41384115, 2025). "We compared the expression differences of CXCL9 and SPP1 between normal cervical tissues and cervical cancer samples." (PMID 40936719, 2025). "Conversely, downregulation of SPP1 expression promotes sensitivity to cisplatin by inhibiting the PI3K/Akt pathway in cervical cancer cells." (PMID 39401197, 2024). "SPP1 is highly expressed in cervical cancer tissues and downregulation of SPP1 induces apoptosis in cervical cancer cells." (PMID 37251946, 2023). "In this study, we compared the C1QC+ and SPP1+ TAMs gene signatures, as well as classic M1 and M2 gene signatures, using transcriptome data of TCGA cervical cancer patients." (PMID 34295336, 2021). "In our study, we attempted to explore the potential mechanism of SPP1 in promoting cervical cancer and its feasibility as a molecular biomarker." (PMID 35058964, 2021). "Next, we validated SPP1 expression of cervical cancer in the Gene Expression Omnibus (GEO) database, including GSE7803, GSE63514, and GSE9750." (PMID 35058964, 2021). "We conducted the logistic regression method to further analyze the relationship between the SPP1 expression level and the clinicopathologic characteristics of cervical cancer." (PMID 35058964, 2021). "In this study, we evaluated the “traditional” M1/M2 gene signatures and the C1QC+ and SPP1+ TAMs gene signatures in cervical cancer." (PMID 34295336, 2021). "In the field of cervical cancer, a previous study found that SPP1 was upregulated in cancer tissues compared with normal tissues." (PMID 34498424, 2021). "Correlation analyzed between SPP1 expression and clinicopathologic characteristics in cervical cancer based on TCGA database." (PMID 35058964, 2021). "We calculated C1QC+ TAMs and SPP1+ TAMs gene signatures in cervical cancer patients and normal cervical tissue from TCGA and GTEX, respectively, using their transcriptome data." (PMID 34295336, 2021). "In conclusion, we demonstrated that SPP1 expression was upregulated in cervical cancer and significantly related to poor survival outcome." (PMID 35058964, 2021). "It is important to determine the role of C1QC+ and SPP1+ TAMs subsets in cervical cancer evolution and progression, and some ongoing experiments are in process." (PMID 34295336, 2021). "We performed logistic regression to evaluate the relationship between the SPP1 expression level and the clinicopathologic characteristics of cervical cancer." (PMID 35058964, 2021). "Although our study is the first work to explore the relationship between SPP1 expression and cervical cancer, it also has some limitations." (PMID 35058964, 2021). "This SPP1 inhibition strategy has been employed in a recent study to overcome cisplatin resistance in cervical cancer." (PMID 33996808, 2021). "Next, we investigated the relationship between SPP1 expression levels and clinical pathological features of cervical cancer." (PMID 35058964, 2021). "Higher expression of SPP1 was strongly related to worse disease-free survival and overall survival in patients with cervical cancer." (PMID 32300605, 2020). "Therefore, this study aims to explore the expression profiles of CXCL9 and SPP1 in cervical cancer tissues and assess their potential clinical value." (PMID 40936719, 2025). "Furthermore, we explored the molecular mechanism of comorbidity between RA and cervical cancer by immunohistochemistry analysis of patients with cervical cancer combined with RA, and successfully identified three key hub genes: SPP1, LYZ, and MCM5." (PMID 41384115, 2025). "Additionally, protein-level analyses, such as Western blot or immunohistochemistry (IHC), are recommended to confirm the expression levels of RNF2 and SPP1 in cervical cancer tissues." (PMID 40809844, 2025).
cervical carcinoma (continued). "CXCL9 and SPP1 exhibit prognostic significance in cervical cancer patients." (PMID 40936719, 2025). "This implied that the role of SPP1 in cervical cancer may be less direct or may be subject to post-transcriptional regulation, warranting further investigation into its functional significance." (PMID 40809844, 2025). "This study found that SPP1 is an abnormally expressed gene in the development of cervical cancer." (PMID 35154316, 2022). "PTK2 SPP1 were also related to the progression of cervical cancer." (PMID 36284631, 2022). "Furthermore, the silencing SPP1 inhibits cervical cancer cell proliferation by downregulating the PI3K/Akt signaling pathway." (PMID 36292719, 2022). "It is clear from our study that SPP1 (secreted phosphoprotein 1), also called as osteopontin, is highly upregulated in all the tested cancer samples and also has been reported in other population studies; hence, SPP1 emerges as a potential prognostic biomarker for cervical cancer screening in women." (PMID 33829064, 2021). "Prognostic values of clinical factors and C1QC+ and SPP1+ TAMs gene signatures in cervical cancer." (PMID 34295336, 2021). "Previous studies have proven SPP1 overexpressed in a variety of cancers and can be identified as a prognostic factor, while no study has explored the function and carcinogenic mechanism of SPP1 in cervical cancer." (PMID 35058964, 2021). "Finally, we analyzed the relationship between SPP1 expression and immune infiltration and comprehensively explored its mechanism in inducing and promoting cervical cancer." (PMID 35058964, 2021). "Therefore, we are now working to verify the gene signatures of C1QC+ and SPP1+ TAMs in the clinical specimens of patients with cervical cancer at different clinical stages by utilizing single-cell sequencing technology." (PMID 34295336, 2021). "Experiments proved that inhibiting SPP1 could inhibit proliferation, induce apoptosis and improve the chemosensitivity of cervical cancer cells." (PMID 34498424, 2021). "Additionally, we performed the receiver operating characteristic (ROC) curve to evaluate the feasibility of the SPP1 expression level to distinguish cervical cancer tissues from normal cervical tissues." (PMID 35058964, 2021). "Therefore, our study aimed to explore the expression of SPP1 in cervical cancer tissues and its potential clinical values." (PMID 35058964, 2021). "Therefore, our study revealed the role of SPP1 in cervical cancer and identified a promising prognostic biomarker." (PMID 35058964, 2021). "Among these, SPP1 and CCl21 were found to be potent secretary molecules contributing to the progression of cervical cancer; thus, the current study projects these genes as potential therapeutic targets in general for cervical cancer and in specific for the Indian population." (PMID 33829064, 2021). "Downregulation of CCL21 is attributed to upregulated expression of SPP1 in cervical cancer tissue." (PMID 33829064, 2021). "Furthermore, we investigated the relationship between SPP1 expression and overall survival (OS) of cervical cancer patients." (PMID 35058964, 2021). "We speculate that if C1QC+ TAMs and SPP1+ TAMs gene signatures can divide TAMs of cervical cancer patients into two distinct functional subsets, patients with different levels of C1QC+ TAMs and SPP1+ TAMs gene signatures may have different clinical features." (PMID 34295336, 2021). "Furthermore, we assessed SPP1 expression in cervical cancer in the GEO database, including GSE7803 (Platform: GPL96), GSE63514 (Platform: GPL570), and GSE9750, and the results confirmed that SPP1 was overexpressed in cervical cancer tissues." (PMID 35058964, 2021). "Besides, we found that patients with locally advanced cervical cancer (LACC, Stage IB2-IVA) have lower C1QC+ TAMs signature and higher SPP1+ TAMs gene signature compared with patients with early stage (stage I-IB1) cervical cancer." (PMID 34295336, 2021).